IFITM3 (interferon induced transmembrane protein 3)
Diseases named in the same sentence as IFITM3 in open-access papers (continued):
Sharing a sentence is not in itself a finding about the gene and the disease.
ZIKV infection (14 papers, 2016 to 2024). "Therefore, if trypsin were to remove or alter the function of the IFITM3 transmembrane protein, it is likely that this could contribute to the increased susceptibility of JAr cells to ZIKV infections." (PMID 29985932, 2018). "It was confirmed that IFITM3-expos transported the IFITM3 molecules and inhibited the ZIKV infection in both mother and fetus using cell culture and pregnant-mouse models." (PMID 39553300, 2024). "As anticipated, we found that ZY13 administration induced the expression of type I IFN-Ifnb, and its inducible genes such as Oasl, Cxcl10, and Ifitm3 at 6 hours post ZIKV infection." (PMID 32849457, 2020). "For example, overexpression of IFITM3, an interferon-inducible transmembrane protein, has been reported to prevent ZIKV infection and ZIKV induced cell lysis in HeLa cells." (PMID 29985932, 2018). "Recently, it was discovered that two small membrane-associated interferon inducible transmembrane proteins (IFITMs) IFITM1 and IFITM3 play a protective role against ZIKV infection by inhibiting replication of the virus and preventing cell death." (PMID 29333229, 2016). "Recent literature has demonstrated that during ZIKV infection, the production of several types of interferon and ISGs is increased, and that IFITM1 and IFITM3 are involved in inhibiting ZIKV infection during the early stages of pathogenesis." (PMID 29333229, 2016). "It has been suggested that the exogenous IFITM3 supplied by EVs could be a promising treatment for preventing prenatal ZIKV infection." (PMID 39553300, 2024). "EVs containing IFITM3 were able to be delivered from pregnant mice to the fetuses and suppress ZIKV infection in both mothers and fetuses, while sEVs that overexpress rabies virus glycoprotein were capable of transplacental delivery of anti-ZIKV siRNA to the fetus brain in mice." (PMID 37781396, 2023). "Interestingly, in infected (ENV+) IFNAR2WT iPS-Mφ, IFITM3 was largely undetectable, suggesting that ZIKV infection prevented IFN-I signalling in infected cells, consistent with prior studies." (PMID 36439115, 2022). "Furthermore, several ISGs including IFITM1 and IFITM3 have been reported to inhibit ZIKV infection at the early stage of the viral life cycle." (PMID 32276512, 2020). "IFITM3 is reported to be able to inhibit Zika virus infection in the early viral replication cycle." (PMID 29281729, 2017). "The novel interactions of FNDC3B with IFITM3 and SPTA1, ARPC1B and AGTR2 with IFITM1 may shed light on mechanisms of host invasion underlying cytoskeletal re-arrangements that follow Zika virus infection." (PMID 29333229, 2016). "Similarly, the IFITM3 has been shown to prevent ZIKV infection, which is notable and effective." (PMID 39553300, 2024). "Analysis of >2000 cells per genotype revealed that upon ZIKV infection in IFNAR2WT iPS-Mφ, IFITM3 was predominantly expressed in uninfected bystander (ENV-) cells, consistent with paracrine regulation of IFITM3 expression." (PMID 36439115, 2022). "In contrast, IFITM1, which is suggested to inhibit early ZIKV infection, was induced at very low levels by ZIKV while IFITM3, which is reported to prevent ZIKV-induced HeLa cell death, was not induced in ZIKV-infected hBMECs." (PMID 28698279, 2017). "Yet, combined transfection of siRNAs directed towards all three different target ISGs (IFIH1, TMEM2, and IFITM3) induced a significant increase in ZIKV replication in pDCs, consistent with an important role of these ISG for restriction of ZIKV infection in pDC." (PMID 32415086, 2020). "Taken together, our findings indicate that there is a robust IFN-I-mediated antiviral effect on ZIKV infection, particularly for American viruses, that is not due to IFITM3." (PMID 32370187, 2020).
breast carcinoma (11 papers, 2013 to 2025). "To date, there is only one report that suggested IFITM3 as one of the significantly upregulated CSCs-related genes in MDA-MB-231 breast cancer cells by single-cell RNA sequencing." (PMID 35941699, 2022). "In the following years, upregulation of IFITM3 in tumor tissues in comparison with paratumor tissues was confirmed in multiple cancers, such as gastric cancer, breast cancer, prostate cancer, and lung cancer." (PMID 34456915, 2021). "Downregulation of the expression of IFITM3 inhibited the growth of breast cancer cells and colony formation." (PMID 34659578, 2021). "In addition, our analysis identified an IFN-responsive neutrophil population with high expression of IFN-responsive genes (Ifit3, Ifit1, Ifit3b, Ifi47, Ifitm3, Rsad2, Isg15, and Isg20), which is more present in metastatic lung of breast cancer." (PMID 37483625, 2023). "In addition to their connection with DNA-damaging agents, IFITM1 and IFITM3 are positively correlated with the development of aromatase inhibitor resistance in breast cancer cells." (PMID 36466909, 2022). "Interestingly, IFITM1 and IFITM3 levels positively correlate with the ER and PR status of breast cancer tissues." (PMID 36466909, 2022).
dengue (11 papers, 2015 to 2025). "Upregulation of IFITM3 in platelets from patients infected with Delta variant as well as dengue and influenza viruses has been reported." (PMID 37828997, 2023). "IFITM3 expression is increased in megakaryocytes and platelets during acute dengue and COVID-19 infections, inhibiting, for instance, DENV entry and replication in megakaryocytes." (PMID 39354676, 2025). "We recently demonstrated that IFITM3 increases in megakaryocytes and platelets during dengue and COVID-19 infection and limits dengue virus entry into the cytoplasm of megakaryocytes, resulting in reduced viral replication." (PMID 36194487, 2022). "Ifitm3 is an antiviral protein that has been shown to induce innate immune response against influenza A, West nile, rift valley fever, dengue and vesicular stomatitis viruses." (PMID 28446152, 2017). "Higher levels of induced transmembrane protein IFITM3 mRNA were observed in platelets during influenza A/H1N1 and dengue." (PMID 35842415, 2022).
gastric cancer (11 papers, 2015 to 2024). A primary or metastatic malignant neoplasm involving the stomach. "Vimentin, a mesenchymal marker is downregulated in IFITM3-/- gastric cancer cells, suggesting a direct association between these proteins." (PMID 33364194, 2020). "has revealed that the IFITM3 can expand malignant progression, promote cancer stemness and chemoresistance of gastric cancer by targeting MET/AKT/FOXO3/c-MYC axis." (PMID 37304304, 2023). "Previous studies found that HPP1, VEZT and IFITM3, which contain a similar transmembrane domain to that of TMEM196, were hypermethylated associated with downregulation in colorectal cancer, gastric cancer and melanoma, respectively." (PMID 26056045, 2015). "Previous research has shown that IFITM3 is upregulated in gastric cancer, which is correlated with tumor invasion and metastasis." (PMID 26539332, 2015). "Additionally, IFITM3 overexpression has been shown to promote gastric cancer growth, through the activation of several pathways, resulting in increased proliferation, invasion, and metastasis." (PMID 37249750, 2023). "Although IFITM3 had been reported to engage in different regulatory signaling pathways to exert oncogenic functions in several other cancer types, IFITM3 was only suggested to be a potential target of the Wnt/β-catenin signaling in gastric cancer." (PMID 35941699, 2022). "Furthermore, IFITM3 expression increased in gastric cancer, and colorectal tumors." (PMID 29088728, 2017). "Moreover, IFITM3 up-regulated in gastric cancer, and colorectal tumors." (PMID 29088728, 2017). "IFITM3 knockdown reduces matrix metallopeptidase 9 and 2 (MMP9 and MMP2) in hepatocellular and gastric cancer cell lines." (PMID 33364194, 2020). "Using isobaric mass tag-based quantitative proteomics approach, we identified IFITM3, an interferon-induced transmembrane protein that was highly expressed in micro-dissected gastric cancer (GC) tumor regions relative to adjacent non-tumor epithelia." (PMID 35941699, 2022).
prostate carcinoma (11 papers, 2019 to 2025). A carcinoma that arises from epithelial cells of the prostate gland. "In prostate cancer, for instance, IFITM3 facilitated tumor progression and bone metastasis via TGF-β-Smads-MAPK pathway; as IFITM3 was proposed to serve as a PIP3 scaffold protein to amplify PI3K signaling in B cells." (PMID 35941699, 2022). "IFITM3 promotes cancer cell proliferation, migration, and metastasis through the TGFβ signaling pathway in prostate cancer cells and facilitates type 2 helper T cell differentiation as well as tumor-associated antigen presentation." (PMID 35884546, 2022). "Moreover, ESS2 expression was highly correlated with adenosine deaminase acting on RNA (ADAR), IFN-inducible transmembrane protein (IFITM) 2, and IFITM3 in patients with prostate cancer." (PMID 37524814, 2023). "IFITM3 promotes bone metastasis in prostate cancer by activating TGF-β signaling." (PMID 34650128, 2021). "IFITM3 promotes bone metastasis of prostate cancer cells by mediating activation of the TGF-β signaling pathway; however, knockdown of IFITM3-induced apoptosis and inhibited their migration." (PMID 40681213, 2025). "In the Oncomine database, we discovered that IFITM3 was highly expressed in several cancers but expressed at low levels in BLCA and prostate cancer." (PMID 34456915, 2021). "Many of the immune response related (e.g., IRF8, JAK3, PTGER4, RELB, IFITM3) and part of the lipid metabolism related genes (e.g., NR1H4, PPARGC1B, PLIN1, HSD17B14) were identified to be adaptive which addressed their significance for prostate cancer." (PMID 36809527, 2023). "IFITM3 is thus a regulator of the TGFβ/Smad/MAPK signaling pathway through the direct interaction between IFITM3 and Smad4, promoting the EMT, cell proliferation, migration and bone metastasis in prostate cancer." (PMID 36466909, 2022).
schizophrenia (11 papers, 2007 to 2024). A major psychotic disorder characterized by abnormalities in the perception or expression of reality. "Furthermore, overexpression of the immune system-associated gene IFITM3, was found in individuals with EDs, and has also been repeatedly reported to be up-regulated in studies of schizophrenia and autism." (PMID 29958387, 2018). "We found that the expression of Ifitm3 increased the extracellular level of Fstl1, while other studies reported the increased expression of Ifitm3 in the brains of schizophrenia patients." (PMID 30348171, 2018). "Besides, the level of IFITM3 was elevated under schizophrenia and other inflammatory conditions in the brain (Horváth and Mirnics, 2014)." (PMID 36994418, 2023). "IFITM3 also may mediate perinatal immune activation effects and has been discussed as a novel drug target for schizophrenia." (PMID 35948659, 2023). "In addition, multiple candidate genes implicated in schizophrenia or other psychiatric disorders were detected, such as SST, NPY, SLC32A1, HINT1, RELN, and IFITM3." (PMID 29958387, 2018). "Recent studies have indicated that Ifitm3 expression is increased in patients with schizophrenia." (PMID 30348171, 2018). "Interestingly, the elevated IFITM3 mRNA expression has been demonstrated in vascular endothelial cells of the BBB in the brains of patients with schizophrenia." (PMID 26633355, 2015). "Given that IFITM3 expression is up-regulated in the brains of patients with schizophrenia and ASD, it is proposed that IFITM3 might be a novel drug target for the treatment of these neurodevelopmental disorders." (PMID 26633355, 2015). "In addition, some studies have reported that IFITM3 mRNA is abundantly expressed in the meninges and blood vessels of the forebrain cortex of patients with schizophrenia, and it is negatively correlated with the level of gamma aminobutyric acid (GABA)-related mRNA." (PMID 37602193, 2023). "Interestingly the same work reveals ‘an intrinsic enrichment’ for interferon-induced transmembrane factor (IFITM3), which is enriched in postmortem schizophrenia brain and may reflect increased neuroinflammation, and oxidative stress." (PMID 35948659, 2023). "In particular, IFITM2, IFITM3, SERPINA3, and GBP1 showed increased mRNA levels in schizophrenia (p-values from qPCR ≤ 0.01)." (PMID 17822540, 2007). "As it has been suggested that schizophrenia may be the consequence of a vascular-inflammation, we studied the mRNA levels of SERPINA3, IFITM2, IFITM3, and GBP1 in a human endothelial cell line (TIME), before and after stimulation with TNF-α." (PMID 17822540, 2007). "Our results give additional support to the inflammatory hypothesis for schizophrenia and provide four biological markers for the disease likely to be directly involved in inflammatory processes, namely GBP1, SERPINA3, IFITM2, and IFITM3." (PMID 17822540, 2007). "Both these analyses confirmed that mRNA levels of SERPINA3, IFITM2, IFITM3 and GBP1 were increased in schizophrenia and were not simply the consequence of an infection immediately prior to death." (PMID 17822540, 2007).
colorectal cancer (10 papers, 2015 to 2026). A primary or metastatic malignant neoplasm that affects the colon or rectum. "In colorectal cancer, research indicates that IFITM3 expression is modulated via the IFN-γ/STAT1 pathway, which plays a significant role in immune escape by influencing the stability of regulatory T (Treg) cells and the maintenance of immune homeostasis." (PMID 40909948, 2025). "IFITM3 is expressed in gastric, liver, pancreatic, and colorectal cancers, and it is a poor prognostic marker in pancreatic ductal adenocarcinoma." (PMID 40909948, 2025). "We observed that tumor samples had upregulated IFITMs including IFITM1, IFITM2, and IFITM3, consistent with previous observations in colorectal cancer." (PMID 29088818, 2017). "In addition, expression of Wif1, an intermediate of Wnt signaling, and IFITM3 are increased in a colorectal cancer induction model—supporting a functional relationship between Wif1 and IFITM3 in cancer initiation." (PMID 33364194, 2020). "In colorectal cancer, phosphorylated CTD interacting factor 1 (PCIF1) modulates colorectal cancer growth and response to anti-programmed cell death 1 (PD-1) in a context-dependent mechanism in which PCIF1 directly targets FOS, IFITM3, and STAT1 via N6,2′-O-dimethyladenosine (m6Am) modifications." (PMID 40681213, 2025).
melanoma (8 papers, 2013 to 2024). A malignant, usually aggressive tumor composed of atypical, neoplastic melanocytes. "Only the module turquoise had a significant enrichment (p = 0.009) of genes whose homologs displayed prognostic value in melanoma, such as Oca2, Samhd1, Nlrc5, Irf1, Ifitm3, Sp100, Dram1, Rtn1, Tcaf2, Parp10, and Grin3a." (PMID 32831131, 2020). "Moreover, Irf1, Ifitm3, and Sp100 are involved in the interferon-mediated response that plays a role in antitumor immunity in melanoma." (PMID 32831131, 2020). "Some of the top upregulated genes included Interferon Induced Transmembrane Protein 3 (IFITM3), Preferentially Expressed Antigen in Melanoma (PRAME), and Deleted in Azoospermia-like (DAZL)." (PMID 38468866, 2024). "Similar situation has come under observation in human melanoma, and it is deemed dynamic promoter methylation adds an additional layer of complexity to the IFN-α key response genes like IFITM3 be required for comprehensive control of the IFN-α response." (PMID 24370119, 2013). "It was found that IFITM3 not only was highly expressed in mononuclear macrophages, but also in those nonimmune and melanoma cells in the microenvironment." (PMID 37304304, 2023).
acute myeloid leukemia (7 papers, 2020 to 2025). Acute myeloid leukemia (AML) is a group of neoplasms arising from precursor cells committed to the myeloid cell-line differentiation. "In addition, high expression of IFITM3 represents adverse prognosis in acute myeloid leukemia, and it can cause B-cell malignancies by motivating PI3K pathway." (PMID 37304304, 2023). "Consistent with literature reports that showed IFITM3 as a prognostic marker associated with progression of head and neck squamous cell carcinoma and acute myeloid leukemia, our study also illustrated that overexpression of IFITM3 was closely correlated with advanced pathological stages in GC." (PMID 35941699, 2022). "To investigate the role of IFITM3 downregulation in acute myeloid leukemia (AML), we first established an AML mouse model by intravenously injecting 5×106 KG-1a cells into NOD/SCID mice via the tail vein." (PMID 40969269, 2025). "However, IFITM3 is also overexpressed in acute myeloid leukemia and predicts adverse prognosis, supporting the assumption that IFITM3 overexpression is a general hallmark of human cancers and not just inflammation." (PMID 34456915, 2021). "However, the recent observation of IFITM3 overexpression in acute myeloid leukemia, a non-solid cancer, supports the hypothesis that IFITM3 overexpression is a hallmark of cancers generally and not just inflammation." (PMID 33364194, 2020).
HCMV infection (7 papers, 2017 to 2025). "However, IFITM3 KO mice experience more severe weight loss and increased mortality compared to WT mice following intraperitoneal cytomegalovirus infection [43•]." (PMID 30662816, 2018). "Herein, we investigated how IFITM3 regulates virus-induced inflammatory responses using a combination of mice and human models of CMV infection." (PMID 36075894, 2022). "Short hairpin RNA (shRNA) knockdown of IFITM1 alone or in combination with IFITM2 and IFITM3 inhibits HCMV infection as they are required for successful formation of the HCMV virion assembly complex (vAC) and production of infectious progeny virions." (PMID 31921100, 2019). "Here, we provide evidence that direct regulation of virus-induced cytokine production is an important additional in vivo function of IFITM3 and, in the context of CMV infection, represents the dominant mechanism through which IFITM3 controls virus-induced disease." (PMID 28240600, 2017). "Overall, our data demonstrate that restriction of virus-induced cytokine production is an important and previously unexplored mechanism through which IFITM3 regulates both virus-induced pathogenesis and that this process exerts a critical influence on the outcome of CMV infection." (PMID 28240600, 2017). "Thus, IFITM3 promoted host survival and control of viral replication during CMV infection." (PMID 28240600, 2017). "Examination of cytomegalovirus infection of several cell types in vitro indicated that this virus is not restricted by IFITM3 [43•]." (PMID 30662816, 2018). "Consistent with observations in HCMV infection, IFITM3 did not directly restrict MCMV replication, but instead acted to limit the overexuberant production of cytokines, in particular IL-6." (PMID 28240600, 2017). "However, as with infection of MyD88-expressing cells, we observed that the UL88-STOP-mCh HCMV infection, in which MyD88 levels are higher, actually downregulated a number of antiviral ISGs, including IFITM1, IFITM2, IFITM3, MX1, and IFI16 (the nuclear sensor that plays a role in sensing of HCMV)." (PMID 40638072, 2025). "However, overexpression of IFITM1, IFITM2 and IFITM3 does not inhibit HCMV infection but rather results in a modest increase in the percentage of infected cells." (PMID 31921100, 2019). "Thus, as observed in HCMV infection, our data suggest that IFITM3 does not directly restrict MCMV cell entry or subsequent replication." (PMID 28240600, 2017). "iPS-DCs were non-permissive to productive HCMV infection after low multiplicity of infection (MOI = 5), irrespective of IFITM3 expression." (PMID 36075894, 2022). "Finally, we generated primary blood monocyte-derived DCs (mDCs) from human donors genotyped for the IFITM3 SNP rs12252 and stimulated cells with HCMV, with these cells being non-permissive to HCMV infection similarly to iPS-DCs." (PMID 36075894, 2022).